LINC01833 (long independently transcribed non-coding RNA 1833)
Synonyms: RP11-89-K21.1; K21.1; RP11-89
Gene: Long non-coding RNA gene on chromosome 2 (44,921,054 to 44,939,344, reverse strand). Ensembl gene ENSG00000259439.
Gene Ontology:
Biological process: regulation of gene expression
Diseases named in the same sentence as LINC01833 in open-access papers:
LINC01833 is named in the same sentence as 7 diseases in open-access papers, as found by Europe PMC text mining. Sharing a sentence is not in itself a finding about the gene and the disease. The quoted sentences say what the papers report.
lung carcinoma (3 papers, 2023 to 2024). "LINC01833 is significantly upregulated in lung cancer, and LINC02321 is significantly upregulated in bladder cancer." (PMID 38609663, 2024). "Nonetheless, additional research is necessary to gain a comprehensive understanding of how LINC01833 operates in lung cancer." (PMID 38011277, 2023). "Overexpression of LINC01833 improves the proliferation and invasion ability of lung cancer cells, as well as promotes the transition from epithelial to mesenchymal state." (PMID 36874011, 2023).
cervical cancer (1 paper, 2024). A primary or metastatic malignant neoplasm involving the cervix. "Experimental studies have shown that LINC01833 and LINC02321 are also upregulated in cervical cancer, and interference with their expression through siRNA transfection significantly reduces cell proliferation and migration capabilities." (PMID 38609663, 2024). "We observed significant upregulation of LINC01833 and LINC02321 in cervical cancer cell lines indicating that LINC01833 and LINC02321 may be potential role in cervical cancer development." (PMID 38609663, 2024). "Furthermore, compared to the NC, the knockdown of LINC01833 and LINC02321 significantly decreased the migration capability of cervical cancer cells." (PMID 38609663, 2024).
lung adenocarcinoma (1 paper, 2021). A carcinoma that arises from the lung and is characterized by the presence of malignant glandular epithelial cells. "LINC01833, also names RP11-89, was identified aberrantly expressed in lung adenocarcinoma and closely related to the Wnt pathway." (PMID 33531988, 2021).
tumor (2 papers, 2021 to 2022). "Role of LINC01833 was further investigated by knocking down LINC01833 in tumor xenograft mice model." (PMID 35441574, 2022).
cancer (1 paper, 2023). A tumor composed of atypical neoplastic, often pleomorphic cells that invade other tissues. "Specifically, LINC01833 can promote these activities by modulating the MiR-519e-3p/S100A4 axis and has shown promise as a biomarker for predicting cancer patient prognosis." (PMID 38011277, 2023).
LINC01833 also shares sentences with these, for which no sentence is quoted: bladder cancer (1 paper); breast carcinoma (1).